BAP1 (BRCA1 associated deubiquitinase 1)
Diseases named in the same sentence as BAP1 in open-access papers (continued):
Sharing a sentence is not in itself a finding about the gene and the disease.
cancer (continued). "The second gene, BAP1, has been shown to predispose to various cancers of different embryonic origins, among which the core tumoral spectrum is composed of cutaneous and ocular melanoma, RCC, and mesothelioma." (PMID 34067022, 2021). "BAP1 mutations have also been associated with a cancer syndrome known as BAP1 cancer predisposition syndrome." (PMID 34771510, 2021). "Consistently, restoration of miR‐223 (3p) in BRCA1, BAP1‐deficient cancer cells is synthetic lethal, probably due to repression of NHEJ components." (PMID 32954644, 2021). "Loss of the tumor suppressor BAP1 is linked to development of a distinct set of cancers, making BAP1 an interesting target to study." (PMID 34591877, 2021). "Patient 2 underwent genetic testing due to her known familial MSH6 mutation and family history of cancer concerning for germline BAP1 mutation." (PMID 33541411, 2021). "As a result of this molecular ambiguity, it has been difficult to determine molecular sensitivities or synthetic lethalities for BAP1-mutated cancers." (PMID 34186021, 2021). "From comprehensive profiling of MPM high-risk families, BAP1 germline mutations emerge as generally associated with less aggressive disease and a 3.5/7-fold improved survival, while in other cancer types, they are associated with poor prognosis." (PMID 33802313, 2021). "This implies that cancer cells employ alternative machinery to avoid the cellular dysfunctions of BAP1 loss." (PMID 33919439, 2021). "BAP1 acts as a tumor suppressor gene and mutations disrupting its deubiquitinase activity or its nuclear localization abolish this function and drive cancer development." (PMID 34199544, 2021). "Some studies have revealed the molecular mechanisms by which cancer cells suppress cell death induced by BAP1 loss." (PMID 33919439, 2021). "Our finding that BAP1 directly regulates the extrinsic apoptotic pathway will provide new insights into the role of BAP1 in the development of MPM and other cancers with frequent BAP1 mutations." (PMID 34597666, 2021). "The common biological pathways highlighted by our results suggest possible shared co-susceptibility to CMM and RCC and possibly other cancers, like that underlaid by the BAP1 gene." (PMID 34067022, 2021). "It is possible that the silencing role of H2AK119ub1 causes widespread repressive pathogenic effects in BAP1 mutant cancers." (PMID 34186021, 2021). "Of 87 patients, 21 patients were analyzed by NGS with 48 selected cancer genes including GNA11, GNAQ and FBXW7, and 66 patients were analyzed for mutations by NGS with 592 cancer genes including BAP1 and SF3B1 mutations as well as MYC amplification." (PMID 34830903, 2021). "Most cancer-associated ASXL1 mutations enhance the catalytic function of BAP1, and therefore decrease levels of H2AK119Ub." (PMID 33105797, 2020). "Somatic mutations in BAP1 occur most frequently in pleural and eye cancers (21% and 32%, respectively; as annotated in the Catalogue of Somatic Mutations in Cancer (COSMIC) database)." (PMID 33105797, 2020). "We found that deletion and heterozygous loss of Bap1 in Pdx1Cre;KrasG12D and Ptf1αCre;KrasG12D mice accelerated cancer progression and shortened survival." (PMID 32541668, 2020). "In contrast to the aetiology of cancers associated with mutations in BAP1, mutations in ASXL1 and ASXL2 are strongly linked to myeloid cell cancers, with ~11% of haematopoietic cancers bearing ASXL1 mutations (COSMIC)." (PMID 33105797, 2020). "Given the increased risks and aggressiveness of cancer development and progression in patients with BAP1 germline variants, understanding how variants in BAP1 affect function will aid interpretation of uncertain variants." (PMID 33240524, 2020). "Our results suggest compromised BAP1 function among the pathogenic variants carriers, which results in altered migration capabilities of the cancer cells, akin to the loss of BAP1." (PMID 33240524, 2020).
cancer (continued). "Classification of novel BAP1 germline variants allows clinicians to inform predisposed patients and relevant family members regarding potential cancer risks, with appropriate clinical interventions implemented if required." (PMID 33240524, 2020). "Testing bias plays a role as well, as patients with a previous medical history of BAP1-TPDS-associated malignancies are more likely to undergo genetic testing." (PMID 31382694, 2019). "Loss of the putative tumor suppressor BAP1 is a candidate biomarker for adverse prognosis in many cancer types, but conversely for improved survival in others." (PMID 31903168, 2019). "Apart from UM, BAP1 gene expression and survival associations were found to be predictive for the prognosis in several (n = 29) other cancer types." (PMID 31635116, 2019). "In order to minimize the burden for patients, all annual screening should preferably be performed in one day, where patients are screened for BAP1-TPDS-associated malignancies by the ophthalmologist, dermatologist, and radiologist." (PMID 31382694, 2019). "Taken together, these findings will pave the way to evaluate BAP1 in a variety of other human cancers with a shared mutational spectrum." (PMID 31635116, 2019). "Both somatic and germline mutations in the BRCA1 associated protein-1 (BAP1) gene have been observed in many cancers." (PMID 30716094, 2019). "BAP1 expression was linked to ERG-fusion type cancers, with strong BAP1 staining in 12% of ERG-negative, but 30% of ERG-positive cancers (p<0.0001)." (PMID 31903168, 2019). "Diagnostic testing of BAP1 is needed to notify individuals carrying a pathogenic variant of BAP1 and their families of their increased cancer risk." (PMID 31382694, 2019). "Treatment of cancer cell lines harbouring nonsense mutations in BAP1 with rTRAIL resulted in markedly reduced cell viability compared with cancer cell lines harbouring missense mutations." (PMID 29345617, 2018). "While the presence of germline BAP1 mutations in cancers associated with BAP1-TPSD is well documented, the role of somatic mutations in this syndrome is not well studied." (PMID 30477459, 2018). "If a BAP1 mutation is present, then screening and early detection of BAP1-associated cancers can be undertaken." (PMID 30001711, 2018). "There were eight cases that carried a germline mutation with information on personal or familial cancers; all had a positive history of BAP1-TPDS." (PMID 30477459, 2018). "Our findings showed that genetic mutations are involved in BAP1 down-regulation, leading to promotion of the invasive character of cancer cells and poor prognosis in GBC." (PMID 30395583, 2018). "Cancers that develop in carriers of germline BAP1 mutations are less aggressive, have a better prognosis and improved survival." (PMID 30001711, 2018). "BAP1 is a tumor suppressor gene deleted or mutated in various human cancer types, including breast, lung, renal cell carcinoma, metastatic uveal melanomas, and malignant pleural mesotheliomas." (PMID 29686263, 2018). "BAP1 nuclear localization and its catalytic activity are essential for its growth-suppressive features, and it is inactivated or mutated in several cancers." (PMID 28659380, 2017). "In our previous study, we have reported that cancer-associated BAP1 catalytic N-terminal domain mutations abrogate its cellular functions due to the formation of β-amyloid aggregates." (PMID 28935764, 2017). "Most cancer-associated ASXL1 mutations give rise to truncated proteins that retain the amino-terminal BAP1 (BRCA1 associated protein 1)-interacting region of ASXL1, but lose the carboxy-terminal PHD domain." (PMID 28055972, 2017). "Similar to BRCA1/2 deficient cancers, mutation in the BAP1 gene leads to a deficient HR pathway and increases the reliance on other DNA repair pathways." (PMID 28756516, 2017).
cancer (continued). "Based on the homology-modeled BAP1 structure, we have identified a few BAP1 residues which possibly play a crucial role in ubiquitin interaction of which a few mutations have been identified in many cancers." (PMID 28935764, 2017). "Germline BAP1 mutations have been extensively studied, where they have been found to cause hereditary cancer susceptibility." (PMID 29166932, 2017). "BAP1 has generated much attention owing to the consistent findings of rare germline or somatic mutations in a wide-range of cancer sites." (PMID 29088836, 2017). "Inactivation mutations in BAP1 have been associated with the pre-disposition and outcomes of many malignant tumors." (PMID 28404968, 2017). "Strikingly, a large-scale systematic review found that patients with BAP1 mutations face increased mortality, both general and cancer-specific, as well as increased likelihood of cancer relapse." (PMID 29166932, 2017). "Enhanced sensitivity to PARP inhibition has been reported in BAP1−/− cells compared with BAP1+/+ and BAP1+/− cells, as well as in cancer cells harboring inactivating mutations in BRCA1 or-2." (PMID 28122578, 2017). "We examined the cancer history in BAP1 variant carrier cases, comparing groups with predicted deleterious variants, benign variants, and no variants." (PMID 28062663, 2017). "Compared to the reported somatic frameshift mutations of BAP1 in the Catalogue of Somatic Mutations in Cancer (COSMIC) database, the neo-antigen of the Bap1 protein is an ideal biomarker for molecular diagnosis and precisely subtyping of MM." (PMID 27187383, 2016). "Three genes with mutations were known cancer associated genes (BAP1, ARHGAP35 and SPEN), but they were mutated in a single sample each, and were missense variants with uncertain functional effects." (PMID 27494029, 2016). "A search of the Catalogue of Somatic Mutations in Cancer (COSMIC) database also revealed that 53.2% of mutations in BAP1 were frameshift indels with neo-peptide formation." (PMID 27187383, 2016). "BAP1's function has been implicated in various other cancer types such as uveal melanoma, clear cell renal cell carcinoma, and cutaneous melanocytic tumors." (PMID 28191281, 2016). "Recently, BAP1 germline mutations have been reported in families with combinations of these same cancers." (PMID 25830670, 2015). "Synthetic lethal approaches offer new opportunities to exploit essential survival pathways in cancer cells with BAP1 loss-of-function." (PMID 25970771, 2015). "Her relatives and descendants are now been closely monitored for early cancer detection and are being tested for germline BAP1 mutations." (PMID 26683624, 2015). "Our study unambiguously demonstrated that cancer associated catalytic domain BAP1 mutations destabilize protein structure leading to formation of beta amyloid aggregates." (PMID 26680512, 2015). "This provides a clear mechanism by which BAP1 loss-of-function alters cancer cell sensitivity to specific HDAC inhibitors." (PMID 25970771, 2015). "The cancer-associated mutants and BAP1 wild type were overexpressed in HEK 293T cells to assess Hsp90 and Hsp70 expression by western blot." (PMID 26680512, 2015). "Oligomer A11 antibody specifically binds to the prefibrillar protein aggregates and here we have demonstrated that BAP1 and cancer associated mutants overexpressed in HEK293T cells showed strong reactivity against A11." (PMID 26680512, 2015). "The question remains however elusive as how aggregation of mutant BAP1 is linked to cancer pathogenesis." (PMID 26680512, 2015). "In summary, it is clinically relevant to identify carriers of BAP1 mutations and patients who developed cancer in a background of germline BAP1 mutations." (PMID 26683624, 2015). "In cellular condition, reactivity of oligomer specific antibody (A11) with cancer-associated mutants of BAP1 demonstrated that they form prefibrillar aggregates." (PMID 26680512, 2015).
cancer (continued). "The cancer associated mutants up-regulate heat shock response and activates transcription of genes normally co-repressed by BAP1." (PMID 26680512, 2015). "Our work establishes a mechanism by which BAP1 loss alters sensitivity of cancer cells to HDAC inhibitors." (PMID 25970771, 2015). "At present, the common link between MM and ccRCC is limited to the fact that both cancers share a relevant percentage of Bap1 mutational loss." (PMID 28548074, 2014). "Recently, its importance was further emphasized as an extensive cancer sequencing study found BAP1 to be one of seven genes whose mutation is the most indicative of poor prognostic outcome." (PMID 24748658, 2014). "Though there have been many types of cancer associated with germline BAP1 mutation, the full spectrum of disease association is yet to be ascertained." (PMID 23977234, 2013). "Whole-exome-sequencing identified a BAP1 splice mutation (c.581-2A>G) in an individual with UMM from a Danish family predisposed to developing UMM as well as a host of other cancers." (PMID 23977234, 2013). "Aside from the striking incidence of cancer, this family presents with other clinical features that have become indications of BAP1 mutation." (PMID 23977234, 2013). "In parallel with our study, Wiesner and colleagues reported germline BAP1 mutations in two unrelated families with “atypical melanocytic tumors” and other cancers." (PMID 22935333, 2012). "Other investigators independently confirmed the association of germline BAP1 mutations and other cancers in additional families." (PMID 22935333, 2012). "We demonstrate that germline BAP1 mutations are associated with a significant increased overall risk of cancer and particularly of MM, UVM and CM." (PMID 22935333, 2012). "In fact, because of the relatively high incidence of carcinomas in the general population, a larger number of BAP1-mutant family members have to be studied before ruling out the possibility that additional cancers are linked to the BAP1 cancer syndrome." (PMID 22935333, 2012). "Loss-of-function mutations within BAP1 and its subunits were frequently observed in many types of cancers, which may contribute to the development of resistance to immunotherapy." (PMID 39817454, 2025). "In both mouse embryonic stem cells and human cancer cell lines, the transcriptional defect induced by BAP1 depletion or catalytic-inactive mutations could be fully rescued by PRC1 depletion." (PMID 39817454, 2025). "This inhibits autophagy in cells derived from various cancer types with BAP1 mutations." (PMID 40754831, 2025). "Here, we identified an autophagic vulnerability in cancers with BAP1 mutations involving the oncogenic tyrosine kinase SRC and the autophagy protein BECN1 that can be therapeutically targeted, opening the possibility of novel treatments specific for tumors with BAP1 loss." (PMID 40754831, 2025). "In addition, various other cancers have significant loss of BAP1, including mesothelioma, clear cell renal cancer, and cholangiocarcinoma." (PMID 41022584, 2025). "When BAP1 functions properly, it helps maintain genomic stability and prevents the accumulation of mutations that could drive cancer development." (PMID 39817454, 2025). "Indeed, this epigenetic effect was particularly pronounced for IL20RB and WT1 in the presence of BAP1 somatic cancer driver mutations (Fig. EV5)." (PMID 39592856, 2024). "However, we additionally identified the relationship between the epigenetic regulation of EMT genes and BAP1 somatic cancer driver mutations in ccRCC." (PMID 39592856, 2024). "Moreover, BAP1 mutants associated with cancer were found to lose their ability to repress SLC7A11 and to promote ferroptosis." (PMID 38267442, 2024). "As BAP1 somatic mutations were also associated with LF2 levels, we evaluated if this epigenetic effect could be modulated by BAP1 somatic cancer driver mutations." (PMID 39592856, 2024).
cancer (continued). "However, among the cancer types that have been studied, consequences of BAP1 loss are pleiotropic and further tissue-specific differences have been documented." (PMID 39554490, 2024). "Recent structures of BAP1/ASXL1 with H2AK119-Ub-containing nucleosomes highlighted the role of many BAP1 mutations identified in cancer, likely to have roles in transcriptional regulation or DNA repair pathways linked to its role as the polycomb-repressive DUB (PR-DUB)." (PMID 38572758, 2024). "Finally, it is worth mentioning that genes involved in ubiquitination processes and linked to cancer were among the significantly correlated genes (BAP1, RNF157, UBQLN2)." (PMID 37730697, 2023). "Some of these mutations, like BAP1, have 100% cancer penetrance and thus are sufficient to cause cancer, others may increase susceptibility to asbestos and to other carcinogens present in the environment." (PMID 37880686, 2023). "Since inactivation of the proteasome by RNAi or use of inhibitors produces aberrant nuclei in C. elegans germline and BAP1 has a regulatory function on ubiquitination of histones, genome instability would be the “hallmark of cancer” behind the BAP1 alterations." (PMID 36980270, 2023). "In this review, we focus on genome stability and summarize the details of the cellular and molecular functions of BAP1 in DNA repair and replication, which are crucial for genome integrity, and discuss the implications for BAP1-associated cancer and relevant therapeutic strategies." (PMID 37009801, 2023). "Likewise, BAP1 gene has been implicated in several types of cancer and is considered pivotal to constrain histone H2A monoubiquitylation (H2AK119ub1) in the genome." (PMID 36923654, 2023). "BAP1 mutations were previously discovered in a small number of breast and lung cancer cell lines, as well as in malignant pleural mesotheliomas, CM, and possibly other cancers such as meningioma." (PMID 36765733, 2023). "This might reveal that cellular BAP1 loss is only advantageous in settings where the cancer cells are under additional stresses, such as upon nutrient limitations in the cancer niche and the onset of the Warburg effect." (PMID 36740402, 2023). "In this review, we summarize the details of the currently known cellular and molecular functions of BAP1 in DNA repair and replication, focusing on genome stability, and we discuss the implications of these functions for BAP1-associated cancer and potential therapeutic strategies." (PMID 37009801, 2023). "The reader may find some discrepancies in the literature, as some articles suggested that the incidence of cancer in carriers of germline BAP1 mutations is around 80%, while we reported that is close to 100%." (PMID 37880686, 2023). "Most of the alterations with confirmed somatic origin resulted in premature termination outside of the regions that are expected to evade nonsense mediated mRNA decay and, therefore, are expected to result in loss of function, which is typical for the spectrum of BAP1 alterations in cancer." (PMID 35920959, 2023). "Hence, such specific pattern of human cancers associated to BAP1 inactivation suggest a role in the response to environmental stressors and indicate a cooperation of predisposing gene mutations and environmental factors in cancer onset and progression." (PMID 36318367, 2022). "The activated senescence program was correlated to increased genomic instability, unbalanced PBMR1/BAP1 mutations, elevated immune cell infiltration, and enhanced immune inhibitory factors (cancer-associated fibroblasts, immune suppression, immune exclusion, and immune exhaustion signaling)." (PMID 35720278, 2022). "Moreover, the literature concerning BAP1 mutation and associated cancers including ccRCC is reviewed." (PMID 35875073, 2022). "BAP1 cancer syndrome is a rare and highly penetrant hereditary cancer predisposition." (PMID 35381901, 2022).